USP53 (ubiquitin specific peptidase 53)
Description:
Deubiquitinase that mediates 'Lys-63'-linked deubiquitination of tight junction proteins, such as MARVELD2 and LSR, and which is involved in the survival of auditory hair cells and hearing. Specifically cleaves 'Lys-63'-linked polyubiquitin chains composed of at least 3 ubiquitin molecules, while it is not able to deubiquitinate substrates with shorter ubiquitin chains: recognizes ubiquitin chain in position S2 and catalyzes en bloc cleavage of polyubiquitin chains from substrate proteins. Probably acts by modulating the barrier properties and mechanical stability of tight junctions via deubiquitination of MARVELD2 and LSR.
Synonyms: KIAA1350; PFIC7
Tractability: Antibody: the Human Protein Atlas places it where antibodies can reach. PROTAC: ubiquitination databases record sites on it.
Gene: Protein-coding gene on chromosome 4 (119,212,128 to 119,295,518, forward strand). Ensembl gene ENSG00000145390.
Subcellular location: Cell junction, tight junction
Subcellular location (Human Protein Atlas): Plasma membrane; Cytosol
Gene Ontology:
Molecular function: cysteine-type deubiquitinase activity; K63-linked deubiquitinase activity; protein binding
Biological process: response to auditory stimulus; sensory perception of sound; protein deubiquitination
Cellular component: bicellular tight junction; cell-cell junction
Genetic constraint (gnomAD): Loss-of-function variants: 63 observed, 85.65 expected, observed/expected ratio (o/e) 0.74, 90% interval 0.6 to 0.91. The upper end of that interval is the gene's LOEUF score, 0.91, which puts it in group 3 of 6, group 1 being the genes least tolerant of losing a copy. Missense variants: 1,099 observed, 1,253.8 expected, observed/expected ratio (o/e) 0.88, 90% interval 0.83 to 0.92. Synonymous variants: 358 observed, 420.36 expected, observed/expected ratio (o/e) 0.85, 90% interval 0.78 to 0.93.
Homologues: Orthologues: chimpanzee USP53 (99% identical), macaque USP53 (96% identical), dog USP53 (86% identical), pig USP53 (84% identical), rabbit USP53 (80% identical), rat Usp53 (76% identical), mouse Usp53 (75% identical), tropical clawed frog usp53 (53% identical), zebrafish USP53 (40% identical), zebrafish usp53b (27% identical), guinea pig Usp53 (8% identical). Paralogues in human: USP54 (34% identical).
Diseases named in the same sentence as USP53 in open-access papers:
USP53 is named in the same sentence as 48 diseases in open-access papers, as found by Europe PMC text mining. Sharing a sentence is not in itself a finding about the gene and the disease. The quoted sentences say what the papers report.
cholestasis (10 papers, 2020 to 2025). Impairment of the bile flow caused by obstruction within the liver, or outside the liver in the bile duct system. "Taken together, our data establish distinct molecular mechanisms of length-dependent decoding of K63-linked polyubiquitin chains and mechanistically connect the loss of USP53 activity to pediatric cholestasis." (PMID 39587316, 2025). "Recently, 14 reports have linked pediatric cholestasis to biallelic mutations in the USP53 gene 34–37." (PMID 39587316, 2025). "Collectively, the results converge into a model in which loss of the USP53 catalytic activity reported herein causes pediatric cholestasis." (PMID 39587316, 2025). "In summary, studies of humans with USP53 variants report variable phenotypes with predominance of cholestasis especially when missing the C-terminal tail that binds to tight junctions of hepatocytes and cochlear cells." (PMID 37895270, 2023). "Previous studies identified a new type of normal-GGT cholestasis caused by autosomal recessive pathogenic variants in ubiquitin-specific peptidase 53 (USP53)." (PMID 34681012, 2021). "Here, we report a novel truncating mutation in the ubiquitin-specific peptidase gene (USP53) causing low-γ-GT (GGT) cholestasis." (PMID 34681012, 2021). "In this study, we not only reinforced the link between USP53 mutations and cholestasis but also presented the description of the clinical features and laboratory data of the patient." (PMID 34681012, 2021). "All this corresponds to biochemically mild cholestasis phenotypes described in patients with mutations in the USP53 gene." (PMID 34681012, 2021). "Disruption of USP53 interferes with its association with these proteins, leading to defective tight junction assembly, weakening of the canalicular membranes in hepatocytes, and subsequent cholestasis." (PMID 41356217, 2025). "Mutations in the USP53 gene can cause cholestasis and deafness and may also be a potential cause of schizophrenia." (PMID 39300775, 2024). "We describe a novel USP53 mutation in a patient with low-GGT cholestasis." (PMID 34681012, 2021). "We suggest that because of the larger number of such reported cases of this disease, USP53-associated cholestasis can be confirmed as a valid disease and should, therefore, be included in the liver gene panels which will further increase the effectiveness of molecular genetic studies." (PMID 34681012, 2021). "However, we cannot be sure that hepatic hemangiomas are the specific symptom of cholestasis caused by mutations in USP53 gene because they are the most common benign liver tumor, the incidence of which ranges from 0.4% to 20% of the total population." (PMID 34681012, 2021). "Thus, our report reinforces the link between USP53 mutations and cholestasis." (PMID 34681012, 2021). "Nevertheless, the detailed clinical, genetic, and histological characterization contributes valuable information to the understanding of USP53-related cholestasis." (PMID 41356217, 2025). "The PubMed database was systematically searched using the keywords “USP53” and “cholestasis”, covering all years available up to December 2024." (PMID 41356217, 2025). "Our findings expand the spectrum of USP53 variants, underscore the relevance of large deletions and emphasize the inclusion of USP53 in genetic panels for idiopathic low-gamma-glutamyl transferase (GGT) cholestasis." (PMID 41356217, 2025). "Given the unexpectedly benign course in this case, we conducted a comprehensive literature review to contextualize the variability in genotype and phenotype of USP53-related cholestasis." (PMID 41356217, 2025). "Initially identified in cholestasis, the tumor suppressive role of ubiquitin-specific peptidase 53 (USP53) had been reported in various cancers recently." (PMID 35654790, 2022). "With this report, we confirm USP53 as the gene for low-GGT cholestasis and describe liver hemangiomas as a possible additional symptom of the phenotype spectrum." (PMID 34681012, 2021).
cholestasis (continued). "In our work, we identified a patient with biallelic “likely pathogenic” variant in USP53, in association with low-GGT cholestasis, which extends the reports of USP53 mutation contributing to intrahepatic cholestasis." (PMID 34681012, 2021). "Mutations in the USP53 gene have previously been associated with a novel autosomal recessive normal and low-GGT cholestasis." (PMID 34681012, 2021). "In particular, USP53 contributes to the maintenance of tight junction integrity through interactions with TJP1 and TJP2, and its loss leads to canalicular membrane instability and cholestasis." (PMID 41356217, 2025). "Notably, while comprehensive genetic screening excluded mutations in other cholestasis-associated genes (ABCB4, FXR, TJP2, MYO5B, and USP53), both cases carried the p.A1028A concurrently with p.V444A." (PMID 40776909, 2025). "There is no information in the OMIM database that mutations in the USP53 gene are associated with cholestasis." (PMID 34681012, 2021). "The proband harbored a novel c.1017_1057del (p.(Cys339TrpfsTer7)) mutation in the ubiquitin carboxyl-terminal hydrolase (UCH) domain of USP53; we describe the clinical and laboratory features of the patient with a rare type of low-GGT cholestasis caused by this variant." (PMID 34681012, 2021). "A similar example refers to a form of early onset cholestasis with hepatomegaly (USP53 gene)." (PMID 33083013, 2020). "Despite carrying a gross deletion in USP53, our patient exhibited a BRIC-like phenotype with intermittent cholestasis and preserved liver function, supporting the notion that USP53-related disease spans a clinical spectrum, and even disruptive variants may present with mild courses." (PMID 41356217, 2025).
breast carcinoma (6 papers, 2020 to 2025). "The analysis from immunohistochemistry staining exhibited that the low expression of USP53 was associated with TNM stage of breast cancers, and more cases with III stage possessed lower USP53 level than those with I/II stages." (PMID 39044157, 2024). "ROC analysis showed that USP53 had good diagnostic accuracy for breast cancer with an area under curve (AUC) of 0.877." (PMID 39044157, 2024). "ROC analysis showed that USP53 had good diagnostic and predictive value in breast cancer." (PMID 39044157, 2024). "We discovered that USP53 expression was linked to poor survival in breast cancer patients." (PMID 37894400, 2023). "The antitumor effect of USP53 has been confirmed in lung and breast cancer, and USP53 expression is downregulated in HCC tissues as well as HCC cell lines." (PMID 40607251, 2025). "Conversely, high USP53 expression, inversely regulated by RCC1, was associated with improved survival (p = 2.9e-0.05 for breast cancer, p = 1.3e-11 for lung cancer)." (PMID 40163507, 2025). "We collected thirty pairs of breast cancer and para-carcinoma tissues, and the real-time PCR result displayed that USP53 was downregulated in breast cancer samples, compared with paired para-carcinoma tissues." (PMID 39044157, 2024). "Bioinformatics analysis showed that USP53 expression was down-regulated in breast cancer tissues compared to normal breast tissues, and patients with low expression of USP53 had worse survival outcomes than those with high expression." (PMID 39044157, 2024). "We found that USP53 expression was downregulated in breast cancer specimens and was negatively correlated with the clinical stages." (PMID 39044157, 2024). "Using CHX to inhibit protein synthesis in breast cancer cells, it was found that overexpression of USP53 delayed the degradation of ZMYND11, while knockdown of USP53 accelerated its degradation." (PMID 39044157, 2024). "The rescue experiments revealed that the anti-tumor role of USP53 in breast cancer cells was at least partially mediated by ZMYND11." (PMID 39044157, 2024). "In order to verify such expression trend, we collected clinical specimens for analysis, and found that both mRNA and protein levels of USP53 were significantly lower in breast cancer tissues than in normal breast tissues." (PMID 39044157, 2024). "USP53 was low expressed in breast cancer tissues, and its expression was negatively correlated with the clinical stage of breast cancer." (PMID 39044157, 2024). "In our study, USP53 overexpression significantly increased the activities of Caspase-3 and Caspase-9, thereby effectively increasing the apoptosis rate of breast cancer cells." (PMID 39044157, 2024). "A total of 1785 USP53-correlated genes were obtained by single gene correlation screening of breast cancer samples from TCGA database." (PMID 39044157, 2024). "Kaplan-Meier Plotter survival analysis suggested that breast cancer patients with low expression of USP53 had significantly worse overall survival (OS) and relapse free survival (RFS) than those with high expression." (PMID 39044157, 2024). "We found that the protein level of USP53 was higher in breast cancer cell lines than in the normal cell line." (PMID 37894400, 2023). "High expression of MGST3 and USP53 was also correlated with poor clinical outcome in HER2-positive breast cancer, although the contribution of these two genes to brain metastasis has not been reported." (PMID 32640677, 2020). "Our data showed that USP53 induced mitochondrial injury and elevated ROS production, which may mediate the apoptosis and proliferation inhibition in USP53-overexpressed breast cancer cells." (PMID 39044157, 2024). "ZMYND11 mediated the function of USP53 in breast cancer progression." (PMID 39044157, 2024). "USP53-ZMYND11 axis may be a good potential biomarker or therapeutic target for breast cancer, which can provide novel insights into the diagnosis, treatment and prognosis." (PMID 39044157, 2024).
breast carcinoma (continued). "These evidences suggested that the downregulation of USP53 may be involved in development of breast cancer." (PMID 39044157, 2024). "We used the TCGA database to analyze the expression of USP family members, and found that USP2, USP6, USP44 and USP53 in breast cancer tissues were significantly down-regulated compared with those in normal breast tissues, among which the first three have been studied in this field." (PMID 39044157, 2024). "Our results suggested that USP53 was low expressed in breast cancer and negatively correlated with TNM stage; USP53 suppressed proliferation and triggered apoptosis of breast cancer cells; USP53 inhibited breast cancer in vitro and in vivo by deubiquitinating ZMYND11." (PMID 39044157, 2024). "USP53 has been shown to play an anticancer role in a variety of solid malignancies, but its role in breast cancer and its mechanism remain unclear." (PMID 39044157, 2024). "USP53 suppressed proliferation and led to apoptosis of breast cancer cells in vitro and in vivo." (PMID 39044157, 2024). "These evidences revealed that the anti-cancer function of USP53 may be mediated by ZMYND11 in breast cancer." (PMID 39044157, 2024). "Ubiquitin-specific peptidase 53 (USP53) has been shown to exert cancer-suppressing functions in several solid tumors, but its role and the underlying mechanism in breast cancer has not been clearly elucidated." (PMID 39044157, 2024). "Kaplan-Meier Plotter survival analysis suggested that USP53 was a prognostic protective factor for breast cancer, and patients with high expression of USP53 could obtain better OS and RFS." (PMID 39044157, 2024). "The results showed that USP53 could significantly inhibit the growth of breast cancer grafts, decrease the proliferation activity of cancer cells, increase the number of apoptotic cells in the tumor, and still regulate the expression level of ZMYND11." (PMID 39044157, 2024). "As shown, the knockdown of USP53 significantly reduced the proliferation of mouse mammary tumors." (PMID 37894400, 2023). "This was consistent with the expression trend of USP53 in lung cancer, renal clear cell carcinoma, hepatocellular carcinoma and esophageal carcinoma, and it acted as a tumor suppressor in these cancers, so we speculated that USP53 should play the similar role in breast cancer." (PMID 39044157, 2024). "USP53-ZMYND11 axis may be a potential breast cancer marker and therapeutic target." (PMID 39044157, 2024). "First, the down-regulation trend of USP53 in six breast cancer cell lines was verified, and stable cell lines (MCF-7 and MDA-MB-231) with USP53 overexpression or knockdown were successfully constructed for follow-up experiments." (PMID 39044157, 2024). "USP53 induced deubiquitination and stabilization of ZMYND11, both of which were prognostic protective factors for breast cancer." (PMID 39044157, 2024). "A total of 562 down-regulated genes in breast cancer were screened from the intersection of GSE10810, GSE42568, TCGA and GEPIA2, including only one member of the USP family, USP53." (PMID 39044157, 2024). "Subsequently, we screened the gene sets of GSE10810, GSE42568, TCGA and GEPIA2 that are significantly down-regulated in breast cancer and whose cross-sets contain only one member of the USP family, USP53." (PMID 39044157, 2024). "The immunofluorescent staining results showed the co-localization of USP53 and ZMYND11, and Co-IP demonstrated their binding in breast cancer cells." (PMID 39044157, 2024). "Bioinformatics analysis showed a positive correlation between the expression of USP53 and ZMYND11 in breast cancer tissues." (PMID 39044157, 2024). "Both USP53 and ZMYND11 were prognostic protective factors for breast cancer." (PMID 39044157, 2024). "Our results demonstrated that USP53 inhibited proliferation and induced apoptosis of MCF-7 and MDA-MB-231 cells in vivo and in vitro, suggesting that the anti-tumor effect of USP53 was extensive in different subtypes of breast cancer." (PMID 39044157, 2024).
breast carcinoma (continued). "However, whether and how USP53 affects the malignant phenotype of breast cancer has not been clear." (PMID 39044157, 2024).
renal clear cell carcinoma (6 papers, 2021 to 2024). "This regulatory trend was consistent with the deubiquitination of cytochrome C, IκBα, and FKBP51 by USP53 in hepatocellular carcinoma, renal clear cell carcinoma and lung cancer studies." (PMID 39044157, 2024). "In similar studies, USP53 was also shown to have proliferative inhibitory effects on lung cancer, renal clear cell carcinoma, hepatocellular carcinoma and esophageal carcinoma." (PMID 39044157, 2024). "Studies have found that USP53 is underexpressed and exerts tumor-suppressive effects in lung cancer, renal clear cell cancer, liver cancer and esophageal cancer." (PMID 39044157, 2024). "USP53 plays a tumor-suppressive role in lung cancer, renal clear cell carcinoma, colorectal cancer, liver cancer, and esophageal cancer but reduces the radiosensitivity of cervical cancer and esophageal cancer to induce radioresistance." (PMID 39300775, 2024). "Studies on clear-cell renal cell carcinoma have shown that ubiquitin-specific peptidase 53 (USP53) expression is downregulated in this tumor." (PMID 38673949, 2024). "As a member of deubiquitinase, ubiquitin-specific peptidase 53 (USP53) is essential for the development of tumors such as hepatocellular carcinoma and renal clear cell carcinoma." (PMID 37894400, 2023). "The expression level of USP53 gene decreases with the increase in the malignant degree of renal clear cell carcinoma, and the patient has a worse prognosis." (PMID 33973730, 2021). "Then, we performed immunohistochemical staining on the tissues of patients with renal clear cell carcinoma and found that the expression of USP53 in tumor tissues was significantly lower than paracancerous tissues." (PMID 33973730, 2021). "Furthermore, USP53 inhibited the progression of clear cell renal cell carcinoma by suppressing the nuclear factor κB (NF‐κB) pathway." (PMID 35654790, 2022). "In addition, USP53 also inhibited the proliferation and migration of clear renal cell carcinoma cells by inactivating the NF-κB pathway." (PMID 35654790, 2022). "In studies of lung cancer, renal clear cell carcinoma, hepatocellular carcinoma and esophageal cancer, patients with high expression of USP53 also showed better survival outcomes, suggesting that USP53 may be a broad-spectrum prognostic protective factor for cancer." (PMID 39044157, 2024).
hepatocellular carcinoma (5 papers, 2022 to 2024). A malignant tumor that arises from hepatocytes. "USP53 enhanced the stability of cytochrome c (CYCS) in hepatocellular carcinoma (HCC) cells by blocking ubiquitination and subsequent degradation to induce apoptosis." (PMID 38904030, 2024). "Consistent with our results, overexpression of USP53 had significant pro-apoptotic effects in the studies of lung cancer, hepatocellular carcinoma and esophageal cancer." (PMID 39044157, 2024). "USP53 also deubiquitinates cytochrome c and promotes apoptosis of hepatoma cells." (PMID 37894400, 2023). "This was consistent with a previous paper, in which the deletion of 33–50 amino acid only abrogated the deubiquitinaiton of USP53 on cytochrome C in hepatoma cells, and did not affect the binding of the two." (PMID 39044157, 2024).